ACE (angiotensin I converting enzyme)
Diseases named in the same sentence as ACE in open-access papers (continued):
Sharing a sentence is not in itself a finding about the gene and the disease.
Hypertension (continued). "Beta Blockers and ACE Inhibitors are used for treating high blood pressure, that is, one of the earliest risk factors of cardiovascular disease (Strauss, Hall, and Narkiewicz 2023) with evidence that especially ACE Inhibitors are underused." (PMID 39887854, 2025). "Studies performed in China have indicated that an effective model of predicting the risk of essential hypertension is the combined effect of ACE gene SNPs rs4291, rs4309, and rs4461142." (PMID 40370871, 2025). "Because of the role of the renin-angiotensin system in blood pressure regulation, ACE is a strong risk factor for essential hypertension." (PMID 40370871, 2025). "In women with HC-induced hypertension compared with women with essential hypertension, the frequency of the rs699T allele was higher, a difference which increased when stratified by the insertion/deletion polymorphism on the ACE gene." (PMID 41323407, 2025). "The current study has shown that ACE I/D polymorphism is associated with the risk of developing hypertension." (PMID 39666621, 2024). "For this class of drugs, the literature presents the case of a 28-year-old woman in her second pregnancy, with hypertension treated with ramipril (an ACE inhibitor) every day, which caused the birth of a 880 g baby girl with an increasing respiratory distress." (PMID 38921258, 2024). "ACE inhibitors, commonly used to treat hypertension and heart failure, have also been implicated, although their role in psoriasis is less well documented." (PMID 39364528, 2024). "Patients with hypertension are also frequently prescribed angiotensin-converting enzyme (ACE inhibitors), a well recognized cause of cough." (PMID 38913018, 2024). "Due to significant contradictory findings in the literature among different populations, further studies should be conducted to determine the association between the ACE I/D polymorphism and susceptibility to hypertension conducted." (PMID 39666621, 2024). "With this study, it can be determined that beta blockers and ACE inhibitors can be preferred to Ca channel blockers in the treatment of hypertension in patients with a high risk of osteoporosis." (PMID 38496804, 2024). "This study showed association of DD genotypes of the ACE gene with hypertension as compared to healthy individuals." (PMID 38356813, 2024). "So, high ACE activity in the blood is detrimental to the heart by enhancing the concentration of angiotensin II and increasing the risk of hypertension." (PMID 39309635, 2024). "Numerous studies have reported a significant risk in the development of hypertension associated with the ACE D allele and DD genotype among Nigerians, Indians, Bangladeshi and Chinese populations." (PMID 39666621, 2024). "Artificial angiotensin-converting enzyme (ACE) inhibitors are employed in hypertension treatment, yet they are associated with a higher incidence of side effects." (PMID 39272559, 2024). "Meanwhile, D alleles have a high ACE plasma level, increased concentrations of angiotensin II, and degradation of bradykinin, which leads to hypertension." (PMID 38917192, 2024). "The association between ACE I/D polymorphism and cardiovascular disease (particularly hypertension) remains controversial, as does its ability to predict the therapeutic effect of ACE inhibitors." (PMID 38707445, 2024). "The angiotensin-converting enzyme (ACE) inhibitor ramipril is effective in managing hypertension; however, there are concerns regarding the risk of severe oxidative stress-induced ovarian damage." (PMID 39765578, 2024). "Hypertension is frequently recognized as an induction factor for CVDs, and it is deemed that ACE and oxidative stress are closely associated with hypertension." (PMID 38540877, 2024). "As per the fitted model, the CYP11B2 r1799998 CT and rs1799998 TT genotype and ACE rs4646994 ID genotype resulted in a decreased risk of developing hypertension, with odds ratios of 0.2017, 0.0538, and 0.4329, respectively." (PMID 38541065, 2024).
Hypertension (continued). "The ACE DD genotype and D significantly increases the risk of developing hypertension in the Ghanaian population." (PMID 39666621, 2024). "The use of ACE inhibitors has been a popular way ameliorate to blood pressure increases to treat hypertension and therefore to lower cardiovascular risk." (PMID 39766777, 2024). "Angiotensin 1-converting enzyme (ACE), an enzyme associated with hypertension, is a dipeptidyl carboxypeptidase responsible for the conversion of Angiotensin I to II." (PMID 39105167, 2024). "Synthetic drugs including ACE inhibitors (e.g., captopril) are already used for the treatment of hypertension, but are unfortunately associated with side effects (hypotension, cough, taste disorders, and angioedema)." (PMID 38397511, 2024). "To explore the association between ACE I/D polymorphism and the development of arterial hypertension in silico, we used a previously created mathematical model of the human cardiovascular and renal systems." (PMID 38707445, 2024). "ACE-inhibitory peptides are crucial in managing hypertension, a major risk factor for cardiovascular diseases." (PMID 39452857, 2024). "D-allele carriers have been reported to exhibit increased ACE concentrations, which significantly affect hypertension, and high ACE activity in the DD genotype of the ACE I/D polymorphism is associated with preeclampsia." (PMID 39194706, 2024). "Results of a meta-analysis indicate that the ACE D allele is associated with hypertension susceptibility in Asian, Caucasian and mixed populations, as well as in the Chinese population, but this association was inconclusive in people of West African descent." (PMID 38707445, 2024). "Increasing age, hypertension, diabetes, liver disease, peripheral vascular disease, and all medications analyzed (except for ACE inhibitors/ARBs and diuretics) were associated with a longer median LOS." (PMID 38345055, 2024). "ACE inhibitors are used to prevent hypertension and mitigate the risk of its consequence in the form of cardiovascular diseases." (PMID 39125365, 2024). "Lisinopril, an ACE inhibitor, effectively manages hypertension but can cause side effects such as dry cough which is well known and upper respiratory symptoms." (PMID 39624172, 2024). "ACE-D/D carriers have higher blood levels of ACE, approximately twice when compared to ACE-I/I individuals, and have been associated with hypertension, ARDS, and in-hospital mortality." (PMID 39194697, 2024). "Previous studies have been conducted in large populations to investigate the pivotal role of the angiotensin-converting enzyme ACE I/D polymorphism in hypertension in an Indian, a Sikh, and an African American population." (PMID 38917192, 2024). "The present study found a significant association between the ACE (I/D) polymorphism and hypertension." (PMID 39666621, 2024). "Common ACE inhibitors such as captopril, lisinopril, enalapril, and ramipril are highly effective in treating hypertension, heart failure, and chronic kidney disease in at-risk patients." (PMID 39452857, 2024). "ACE inhibitors or ARBs are often recommended as first-line treatments for hypertension associated with cancer therapies." (PMID 39685948, 2024). "In the current research, we used a previously created cardiorenal model to examine the association of ACE I/D polymorphism with high blood pressure and evaluate the success of RAAS inhibition in the treatment of hypertension depending on ACE genotype." (PMID 38707445, 2024). "Five variants (CYP11B2 rs179998, AGT rs5051 and rs699, AGTR1 rs5186, and ACE rs4646994) were significantly associated with essential hypertension in the cohort under study." (PMID 38541065, 2024). "The relationship between ACE I/D polymorphism and the pathogenesis of essential hypertension is controversial." (PMID 38707445, 2024). "This study aims to determine the relationship between the ACE I/D polymorphism and the risk of essential hypertension among patients seeking medical attention." (PMID 39666621, 2024).
Hypertension (continued). "The initial drug of choice is an angiotensin-converting enzyme (ACE) inhibitor or angiotensin receptor blocker (ARB) to treat hypertension by targeting the underlying pathogenesis in the activation of the renin-angiotensin-aldosterone system." (PMID 37038580, 2023). "Concerning hypertension treatment, drugs like losartan, captopril, and valsartan from the ACE inhibitor/ARB class were associated with a reduction in mortality, consistent with previous studies." (PMID 38164450, 2023). "Insertion/deletion polymorphisms in the ACE gene have previously been linked to an increased risk of systemic hypertension." (PMID 38002923, 2023). "The present mini review aims to provide an overview of the complex relationships between diet, ACE polymorphisms, and hypertension, focusing on how these interactions affect diverse populations." (PMID 37964928, 2023). "Many researchers are working to study the involvement of genetic polymorphisms in ACE and its subsequent relation with hypertension." (PMID 37389408, 2023). "The overproduction of angiotensin by the activity of ACE leads to a medical condition known as hypertension, and consumption of synthetic drugs causes many side effects and sometimes even death." (PMID 37324400, 2023). "In a meta-analysis of contemporary hypertension trials, ACE inhibitors vs. all comparators reduced all-cause mortality by 10% (P < 0.05), whereas ARBs in a parallel meta-analysis were associated with no reduction in mortality." (PMID 34533690, 2023). "We found that the DD genotype and D allele of the ACE gene predispose to the occurrence of hypertension in our study participants." (PMID 37200278, 2023). "Among all the components, genetic polymorphism in angiotensinogen (AGT) and angiotensin-1-converting enzyme (ACE) are the most reliable candidate risk for hypertension given consistent findings." (PMID 37201134, 2023). "We conclude that hypertension and mutations in the ACE (rs4331) and ACE2 (rs2074192) genes affect the severity of COVID-19." (PMID 37667339, 2023). "Diets with an increased intake of potassium, soy protein, alpha-linolenic acid, and low in sodium have been shown to decrease ACE activity, potentially reducing the risk of hypertension." (PMID 37964928, 2023). "Beyond the systemic hypertension, ACE D/D genotype was significantly associated to cardiometabolic diseases, such as obesity and T2D, which are known risk factors for COVID-19." (PMID 36371754, 2023). "The angiotensin-converting enzyme (ACE) is the key enzyme in controlling blood pressure, and polymorphisms in ACE, the gene encoding this enzyme, have been implicated in the risk for hypertension and CVS diseases." (PMID 37993702, 2023). "In previous studies, the D allele or DD genotype of ACE has been associated with increased enzyme activity and implied susceptibility to diseases, such as hypertension and CVDs, in which there would be greater activity of the enzyme." (PMID 38032879, 2023). "Valerian extract inhibited key enzyme activities that were associated with obesity (lipase), hypertension (ACE), and type 2 diabetes (α-amylase and α-glucosidase), suggesting that it is a potential candidate for the development of functional supplements." (PMID 36766164, 2023). "Inconsistencies were still visible between researchers about the ACE gene I/D polymorphism in hypertension and ischemic stroke complications." (PMID 37034069, 2023). "The goal of this study was to look into the effect of the ACE gene I/D polymorphism on the risk of ischemic stroke in patients with hypertension." (PMID 37034069, 2023). "Among the processes associated with hypertension, angiotensin I-converting enzyme (ACE), which is involved in the kallikrein–kinin system (KKS) and renin–angiotensin system (RAS), plays a pivotal role in the development of hypertension." (PMID 37446242, 2023).
Hypertension (continued). "No previous studies have reported an association of the GNB3 and ACE polymorphisms with hypertension and preeclampsia, specifically in the PPCM population." (PMID 37089887, 2023). "There is a significant correlation between the ACE gene I/D polymorphism and the development of ischemic stroke in patients with a history of hypertension in the Ethiopian population." (PMID 37034069, 2023). "An insertion/deletion (I/D) variant, rs1799752, in the intron of the ACE gene has been linked to hypertension in studies among Tunisians, Egyptians, and black South Africans and has been shown to contribute to ACE-inhibitor-induced adverse reactions." (PMID 38633331, 2023). "Plant-based ACE inhibitors have therapeutic potential in treating hypertension and other anomalies associated with diabetes." (PMID 36803524, 2023). "In Latin America, hypertension prevalence is increasing due to several factors, including aging, a “Westernized” diet, and possible genetic predisposition factors involving the ACE gene." (PMID 37964928, 2023). "Variants in the ACE gene have been linked to increased ACE activity and elevated levels of angiotensin II, a potent vasoconstrictor that contributes to hypertension." (PMID 37416924, 2023). "Arterial hypertension is a major risk factor for heart failure and antihypertensives such as angiotensin converting enzyme (ACE) inhibitors and β-blockers are considered as its first-line treatment." (PMID 41527552, 2023). "The variant has been related to increased susceptibility to migraine, hypertension due to a high saturated fat diet, ACE activity, salt-sensitive hypertension risk, hypertension, atherosclerosis, adiposity and blood pressure, among others." (PMID 37964928, 2023). "Others have found that hypertension treatment, either with angiotensin-converting enzyme inhibitors (ACE-i) or β blockers, was associated with a reduced incidence of fibroids among women with hypertension." (PMID 37628676, 2023). "In the Nutrigenomic Analysis in Twins (NUGAT) study, GG genotype of rs4343 of ACE was associated with increased risk for hypertension and CVS diseases in individuals on high saturated fat diet." (PMID 37993702, 2023). "Inhibition of ACE, the main enzyme in reducing the risk of hypertension, was investigated using extract concentration of 1 mg/mL." (PMID 38066118, 2023). "Is there a difference in the long-term risk of mortality and morbidity outcomes for adults with hypertension starting 1 of 3 antihypertensive treatments: thiazide-type diuretic, calcium channel blocker, or angiotensin-converting enzyme (ACE) inhibitor?" (PMID 38048133, 2023). "In this study, hypertension was found to be significantly associated with the presence of periodontitis, and moreover, the intake of ACE inhibitors was similarly associated with periodontal disease." (PMID 37888091, 2023). "A case-control study among hypertensive patients and normotensive control groups found that the DD genotype and D allele of the ACE gene have had a strong association with a high risk of hypertension in the study population." (PMID 37201134, 2023). "ACE inhibitors are utilized in treating hypertension as they cause vasodilation by preventing the formation of angiotensin II by inhibiting the angiotensin-converting enzyme." (PMID 36771707, 2023). "In young people with hypertension, there is linkage disequilibrium between the rs12709426 site of the ACE gene and the single nucleotide polymorphism of the ACE gene promoter, with the former being associated with EH incidence." (PMID 37091860, 2023). "The most studied ACE polymorphism is rs4343, which, although a synonymous mutation resulting in the same amino acid (Thr776Thr), has been associated with a higher hypertension risk in both healthy and obese subjects." (PMID 37964928, 2023). "Overactivation of this system is implicated in the pathogenesis of hypertension; hence, angiotensin-converting enzyme (ACE) inhibitors are commonly prescribed to treat hypertension." (PMID 38004453, 2023).
Hypertension (continued). "An insertion (I) or deletion (D) of Alu repeat sequence within the intron 16 of the ACE gene, denoted as ID variant (rs1799752), is accounted for 47% of the total variance of serum ACE, and its relation to hypertension has been intensively studied." (PMID 36819141, 2023). "The presence of the Insertion/ Deletion polymorphism in the ACE gene has been linked to a higher probability of developing essential hypertension, including resistant hypertension." (PMID 37416924, 2023). "SNPs of ACE rs4318, rs4343, rs4344, rs4362, and rs4353 have been reported to be associated with an increased risk of developing high blood pressure, coronary heart disease, and myocardial infarction." (PMID 37091860, 2023). "In another study, the ACE D/D allele was associated with low nitric oxide metabolites (nitrite and nitrate) in healthy men with high blood pressure." (PMID 37238156, 2023). "The association of high blood pressure in two patients with the D variant of the angiotensin-converting enzyme (ACE) has been displayed before." (PMID 37900914, 2023). "The DD genotype of the ACE gene polymorphism was found to have a significant association with high blood pressure and blood glucose levels in the study population." (PMID 37200278, 2023). "In alignment with this, supplementary MK application in MK-deficient mice, who underwent 5/6 nephrectomy, restored hypertension, and prompted pulmonary ACE expression." (PMID 36204583, 2022). "Angiotensin converting enzyme (ACE) overactivation is one of the primary causes of hypertension, which leads to cardiovascular disorders all over the world." (PMID 36547528, 2022). "The ACE I/D polymorphism has been associated with higher serum ACE levels, obesity, hypertension, increased cardiovascular risk, and thrombophilia; all clinical conditions related with more aggressive COVID-19 disease." (PMID 35120165, 2022). "Several studies conducted in Nigerian, Chinese, Brazil, Indian, Arabian, and Bangladeshi populations have suggested that there is a strong association between ACE- DD polymorphism with a higher incidence of hypertension." (PMID 36355860, 2022). "Angiotensin-converting enzyme (ACE) inhibitors are among guideline-recommended first-line therapies in patients with hypertension to reduce the related risk of atherosclerotic disease and cardiovascular events." (PMID 36017709, 2022). "The increased EVs with more ACE content act on adjacent VSMCs, causing VSMCs proliferation, and thereby contributing to vascular remodeling and hypertension." (PMID 35832088, 2022). "Antihypertensive therapy using quercetin compound administered continuously can inhibit conversion of ACE from angiotensin I to angiotensin II, which causes vasoconstriction in blood vessels and consequently hypertension." (PMID 40919293, 2022). "The present study depicted that ACE I/D polymorphism was significantly associated with the risk of hypertension." (PMID 36355860, 2022). "To clarify the underlying pharmacological mechanism of BAC on anti-hypertension by targeting ACE/ACE2, we further studied the endothelium-dependent vasorelaxation and vascular inflammation in BAC-treated SHRs." (PMID 35359841, 2022). "Our study found that in the severity outcome, the ACE D allele and older age are risk factors for disease severity, but in the mortality outcome, background disease, specifically hypertension, and older age are risk factors." (PMID 36531237, 2022). "Chitosan, chitin, and their derivatives can serve as the inhibitors of ACE, which is an enzyme linked to hypertension." (PMID 35464014, 2022). "Angiotensin I-converting enzyme (ACE) inhibitor has been associated with a reduction in hypertension." (PMID 36362874, 2022). "Captopril (DrugBank DB01197) and quinapril (DrugBank DB00881) belong to angiotensin-converting enzyme (ACE) inhibitors, which are widely used for the treatment of hypertension and have been associated with reduced risks of COVID-19." (PMID 35991542, 2022).